SIRT2 (sirtuin 2)
Diseases named in the same sentence as SIRT2 in open-access papers (continued):
Sharing a sentence is not in itself a finding about the gene and the disease.
cervical cancer (7 papers, 2016 to 2025). A primary or metastatic malignant neoplasm involving the cervix. "Inhibition of SIRT2 in cervical cancer cells proves to have a beneficial effect by causing cell cycle arrest." (PMID 39815261, 2025). "The differential expression patterns of PCAF and SIRT2 in AMPK-activated cervical cancer cells suggest that acetylation of H3K9 in cervical cancer may be dynamically regulated by acetyltransferases and deacetylases." (PMID 38831454, 2024). "In 2018, a sirtuin rearrangement ligand (SirReals), as a highly potent and isoform-selective Sirt2 inhibitor conjugated to thalidomide, a bona fide cerebellar ligand, a PROTAC was developed to induce the degradation of Sirt2 in HeLa (Cervical cancer) cells and inhibit cell viability." (PMID 36770884, 2023).
Cognitive impairment (7 papers, 2020 to 2024). Abnormal cognition is characterized by deficits in thinking, reasoning, or remembering. "SIRT2 inhibition also improves cognitive impairment in different AD animal models and promotes neuronal survival." (PMID 37721957, 2023). "Recent data support the neuroprotective role played by SIRT2 inhibitors in cognitive impairment, suggesting that SIRT2 has a critical role in neurological diseases, being a potential therapeutic target for most of them." (PMID 37298312, 2023). "When we overexpressed RTN4B in neurons of the hippocampus in the AD mouse model, the abnormal Aβ accumulation and cognitive impairment were ameliorated, consistent with the results of SIRT2 inhibition in vivo." (PMID 32700357, 2020). "To evaluate the role of SIRT2 in cognitive impairment in AD, we first considered that reducing SIRT2 activity rather than its expression levels might represent a more promising therapeutic target for AD." (PMID 32700357, 2020). "Collectively, these results suggest that the inhibition of SIRT2 deacetylation activity may be effective against the cognitive impairment in AD mice, via a reduction of Aβ production by influencing BACE1." (PMID 32700357, 2020). "Several lines of evidence have shown that Sirt2 inhibitor (AGK-2 and AK-7) injection in AD-like mouse models decreased Aβ generation by reducing BACE1 levels, thus leading to an amelioration of cognitive impairment." (PMID 35701718, 2022).
breast tumors (6 papers, 2015 to 2026). "Here, we found that MRE11 is deacetylated by the SIRT2 sirtuin deacetylase and breast tumor suppressor, which promotes DNA binding to facilitate DNA end resection and ATM-dependent signaling." (PMID 41505211, 2026). "Specifically, in moderately differentiated grade 2 breast tumors, SIRT2 expression is very low and G2/M phase transition is deregulated, correlating with poor prognosis." (PMID 30761005, 2019).
Cerebral ischemia (6 papers, 2015 to 2023). Restriction of arterial blood supply to the brain associated with insufficient oxygenation to support the metabolic requirements of the tissue. "In animal models, it was observed that SIRT2 mRNA was upregulated after cerebral ischemia, and by knocking out SIRT2, neurological functions were preserved." (PMID 37684620, 2023). "Although some studies pointed to the pathological role of SIRT2 after cerebral ischemia, the functions of SIRT2 in the ischemic brain are possibly more complicated than only pathological or only neuroprotective." (PMID 34680562, 2021). "SIRT1, SIRT2, and SIRT3 have the highest deacetylase activities and can exert great neuroprotective effects in cerebral ischemia." (PMID 33149812, 2020). "Roles of SIRT2 have been proposed but remain to be defined in both ALS and cerebral ischemia." (PMID 25608039, 2015). "SIRT2 was upregulated during neuronal ischemia in the oxygen-glucose deprivation (OGD)-induced cell model and the MCAO-induced mouse model; notably, downregulating SIRT2 could significantly protect neurons against cerebral ischemia." (PMID 37627275, 2023).
Glucose intolerance (6 papers, 2018 to 2025). Glucose intolerance (GI) can be defined as dysglycemia that comprises both prediabetes and diabetes. "SIRT2 KO mice also displayed dysregulated metabolic function, including increased fat mass and glucose intolerance." (PMID 40925650, 2025). "In the GTT, the glucose excursion curve of WT mice fed a HFD was increased compared to CD, while HFD-fed SIRT2-KO mice showed a tendency (p = 0.06) for aggravated glucose intolerance." (PMID 35743232, 2022). "However, 2-month-old SIRT2-KO male rats exhibited glucose intolerance and decreased insulin secretion in response to glucose challenge compared with WT rats." (PMID 33754030, 2021). "Therefore, glucose intolerance in SIRT2-KO rats is mainly attributed to impaired GSIS due to the deacceleration of glucose metabolism in islets." (PMID 33754030, 2021). "In this current study, the deletion of SIRT2 led to glucose intolerance in chow diet-fed rats." (PMID 33754030, 2021). "In our study, the insulin sensitivity was comparable between SIRT2-KO and WT rats, but blood insulin level after glucose loading was markedly decreased in SIRT2-KO rats, which may explain glucose intolerance." (PMID 33754030, 2021). "It was reported that glucose intolerance was markedly improved in SIRT2-KO mice." (PMID 33754030, 2021). "While NMN treatment ameliorated glucose intolerance in obese HFD-fed mice, Sirt2 knockdown partially negated the blood glucose-lowering effects of NMN in a glucose tolerance test when endogenous insulin secretion was inhibited by somatostatin administration." (PMID 29296001, 2018). "BMM-sEVs transfer miRNA-212-5p to adjacent β cells dor insulin secretion, downregulating sirtuin 2 (SIRT2) in recipient β cells, impairing the SIRT2-mediated Akt/glycogen synthase kinase-3β (GSK-3β)/β-catenin pathway, finally disrupting insulin secretion and glucose intolerance in islet β cells." (PMID 35832790, 2022).
metabolic syndrome (6 papers, 2017 to 2024). A cluster of metabolic risk factors for CARDIOVASCULAR DISEASES and TYPE 2 DIABETES MELLITUS. "It was reported that the expression of SIRT1 and SIRT2 in metabolic syndrome rats was reduced in white adipose tissue at six months old." (PMID 30424542, 2018).
pulmonary fibrosis (6 papers, 2021 to 2024). Chronic progressive interstitial lung disorder characterized by the replacement of the lung tissue by connective tissue, leading to progressive dyspnea, respiratory failure, or right heart failure. "In the aging process, SIRT2 is implicated in both pulmonary fibrosis and vascular fibrosis." (PMID 39226168, 2024). "SIRT2 is involved in the development of idiopathic pulmonary fibrosis (IPF) by regulating the Smad2/3 pathway." (PMID 39226168, 2024). "A previous investigation on the role of SIRT2 in pulmonary fibrosis revealed that SIRT2 expression was upregulated in human embryonic lung fibroblasts treated with TGF-β1." (PMID 37483618, 2023). "In animal model, inhibition of Sirt2 alleviated pulmonary fibrosis and reduced the phosphorylation of Smad2/3 induced by bleomycin." (PMID 34925016, 2021). "Inhibition of SIRT2 alleviates renal tubulointerstitial fibrosis in the mouse model of obstructive nephropathy and pulmonary fibrosis in the ovalbumin-induced allergic airway inflammation murine model." (PMID 34642310, 2021). "On the other hand, a pro-fibrotic action of SIRT2 has been documented in renal and pulmonary fibrosis." (PMID 34642310, 2021). "Inhibition of SIRT2 alleviated fibroblasts activation and pulmonary fibrosis via Smad2/3 Pathway." (PMID 37483618, 2023). "Treatment with the SIRT2 inhibitor AGK2 significantly attenuated the degree of pulmonary fibrosis and reduced the phosphorylation of Smad2/3; therefore, SIRT2 may be involved in IPF development by regulating the Smad2/3 pathway." (PMID 37483618, 2023). "They concluded that most SIRTs are protective against pulmonary fibrosis, except SIRT2, which may play a pro-fibrotic role given the pro-inflammatory effects observed in asthma." (PMID 37483618, 2023). "Next, in order to determine whether Sirt2 plays a role in pulmonary fibrosis, Sirt2 expression was examined in MRC-5 cells treated with the same concentration of TGF-β1." (PMID 34925016, 2021). "In this study, we aimed to evaluate the role of Sirt2 in pulmonary fibrosis." (PMID 34925016, 2021). "However, the limitation of this study is that only small molecule inhibitor was used, and further studies with Sirt2-KO mice are needed to investigate the exact effects of Sirt2 on pulmonary fibrosis." (PMID 34925016, 2021). "In addition, SIRT2 inhibition alleviates fibroblast activation and renal tubulointerstitial fibrosis, while SIRT2 inhibitors can alleviate inflammation and suppress idiopathic pulmonary fibrosis." (PMID 39226168, 2024). "Our results illustrated that Sirt2 possibly regulates Smad2/3 directly or indirectly and lead to higher phosphorylation of Smad2/3 in response to stimulators; Sirt2 may promote the activation of fibroblasts and the development of pulmonary fibrosis through Smad2/3 pathway." (PMID 34925016, 2021). "In the current study, we evaluated the role of Sirt2 in TGF-β1 induced lung fibroblasts activation and bleomycin induced pulmonary fibrosis in mice." (PMID 34925016, 2021). "A SIRT2 inhibitor or the knockdown of SIRT2 expression by small interfering RNA (siRNA) suppressed the expression of the fibro-genic genes α-SMA and fibronectin in TGF-β1-treated fibroblasts and primary lung fibroblasts derived from patients with idiopathic pulmonary fibrosis (IPF)." (PMID 35620467, 2022). "However, to assess the expression of SIRT2 in another fibrotic disease, we reanalyzed the database obtained from liver biopsy specimens from patients with cirrhosis (GSE139602) and lung biopsy specimens from patients with idiopathic pulmonary fibrosis (GSE110147)." (PMID 37777567, 2023). "However, the role of Sirt2 has not been explored in pulmonary fibrosis." (PMID 34925016, 2021).
cognitive decline (5 papers, 2019 to 2025). "Our data reinforces this possibility and, in particular, point toward microglial Sirt2 as a potential therapeutic target to prevent cognitive decline associated to neuroinflammation." (PMID 32625056, 2020). "Cognitive decline was also apparent, as aged SIRT2 KO mice spent less time in the target quadrant in the Barnes maze test." (PMID 40925650, 2025). "SIRT2 regulates BACE1 by deacetylating RTN4B, which, in turn, influences Aβ production and aggregation, ultimately alleviates the cognitive decline of AD." (PMID 32700357, 2020).
endotoxemia (5 papers, 2017 to 2024). "Going well along with a reduced glycolytic activity of macrophages in vitro, SIRT2/3−/− mice had a strong survival advantage during endotoxemia, which was associated with reduced blood levels of cytokines." (PMID 31849939, 2019). "Importantly from a translational perspective, SIRT2/3 deficient mice were protected from endotoxemia." (PMID 31849939, 2019). "Strikingly, SIRT2/3−/− macrophages favor fatty acid oxidation over glycolysis, and SIRT2/3−/− mice are robustly protected from endotoxemia." (PMID 35883885, 2022). "In line with metabolic adaptation and increased numbers of peritoneal B-1a cells, SIRT2/3−/− mice were robustly protected from endotoxemia." (PMID 31849939, 2019). "Importantly, SIRT2/3−/− mice were protected from endotoxemia, contrary to SIRT2−/− and SIRT3−/− mice that behaved like wild-type mice." (PMID 31849939, 2019). "Furthermore, simultaneous deletion of both SIRT2 and SIRT3 influences the metabolism and inflammatory responses of macrophages, while providing protection against endotoxemia; however, a single deficiency in either SIRT2 or SIRT3 has minimal or no impact on antimicrobial innate immune responses." (PMID 39372420, 2024). "Importantly from a translational perspective, SIRT2/3−/− mice were protected from endotoxemia." (PMID 31849939, 2019). "In a severe model of endotoxemia (induced by 25 mg/kg LPS), TNF, IL-6, and IL-12p40 concentrations in blood and mortality rates (88% in both groups, P = 0.69) were strongly increased, but remained similar in SIRT2+/+ and SIRT2−/− mice." (PMID 28894448, 2017). "In a mild model of endotoxemia (induced by an i.p. challenge with 10 mg/kg LPS), TNF and IL-12p40 concentrations in blood and mortality rates (83 vs 100%, P = 0.3) were comparable in SIRT2+/+ and SIRT2−/− mice." (PMID 28894448, 2017). "Consequently, the increased expression of SIRT6 in SIRT2/3−/− macrophages may favor FAO and contribute to dampen the cytokine storm involved in the pathological process of endotoxemia." (PMID 31849939, 2019). "A main observation of this study is that SIRT2 deficiency protected mice from chronic staphylococcal infection, while it neither protected nor sensitized mice to TNF-induced shock, endotoxemia, rapidly lethal E. coli peritonitis and mild K. pneumoniae pneumonia." (PMID 28894448, 2017).
fibrosis (5 papers, 2021 to 2024). the formation of excess fibrous connective tissue in an organ or tissue in a reparative or reactive process. "Aging-associated SIRT2 alternations correlate with HSC activation in viral hepatitis, non-alcoholic fatty liver disease, and fibrosis onset." (PMID 39226168, 2024). "On the contrary, in carbon tetrachloride- and thioacetamide-induced fibrosis mouse models, SIRT2 inhibition represses fibrogenic gene expression in hepatic stellate cells and prevents the development of hepatic fibrosis." (PMID 34642310, 2021). "SIRT2 has an overall positive effect in the liver, because it suppresses hepatic fibrosis and steatosis, and it counteracts ROS generation and mitochondrial dysfunction to restore insulin sensitivity." (PMID 33806509, 2021). "SIRT2 is downregulated in fibrotic kidneys from patients with DKD and CKD as well as in UUO- or uIRI-induced mouse fibrosis models." (PMID 37777567, 2023).
heart failure (5 papers, 2021 to 2025). Inability of the heart to pump blood at an adequate rate to meet tissue metabolic requirements. "The studies demonstrates that SIRT2 functions as a unique negative regulator of the NFAT TF, ameliorating heart failure in SIRT2-deficient mice." (PMID 41567643, 2025). "Plasma SIRT2 level predicts heart failure and MACE post-AMI, by regulating metabolic and inflammatory pathways." (PMID 41567643, 2025). "SIRT2 can affect a variety of cardiovascular diseases, energy metabolism and the ageing of cardiomyocytes, thereby affecting heart failure." (PMID 34028177, 2021). "In support of this, Sirt2 protein expression is shown to be severely decreased in angiotensin-induced heart failure, and Sirt2-KO worsened the outcome in response to chronic pressure overload by TAC." (PMID 33554956, 2021). "SIRT2 can also regulate the activity of NFATc2 to protect the heart from diseases related to ageing of cardiomyocytes and inhibit heart failure." (PMID 34028177, 2021). "Furthermore, following an acute cardiac hypotrophy, plasma SIRT2 levels may be a biomarker for heart failure and other serious adverse cardiovascular events." (PMID 41567643, 2025). "Compared to SIRT1, SIRT3, and SIRT6, studies on SIRT2,541 SIRT4, SIRT5,542 and SIRT7 in heart failure are limited." (PMID 36581622, 2022). "Studies on SIRT2, SIRT4, SIRT5, and SIRT7 might reveal promising research directions for the treatment of heart failure." (PMID 36581622, 2022). "Therefore, we speculate that SIRT2 will promote the deacetylation of PGC1‐α in cardiomyocytes, which will reduce the expression of PGC1‐α and eventually lead to heart failure." (PMID 34028177, 2021).
lung adenocarcinoma (5 papers, 2016 to 2023). A carcinoma that arises from the lung and is characterized by the presence of malignant glandular epithelial cells. "The use of specific SIRT2 inhibitors in lung adenocarcinoma cells induces H4K16ac, contrary to the novel VRK-IN-1 inhibitor, which prevents H4K16ac and a correct DNA damage response." (PMID 36902348, 2023). "In our study, we showed that SIRT2 expression was positively correlated with the overall survival of lung adenocarcinoma patients but negatively correlated with HRD1 expression." (PMID 31932479, 2020). "In contrast, SIRT2 expression was positively correlated with the overall survival of lung adenocarcinoma patients." (PMID 31932479, 2020). "Collectively, these results suggest that Sirt2 deletion enhances the progression of oncogenic KRAS-induced lung adenocarcinomas." (PMID 27637077, 2016). "Additionally, we found that patients with lung adenocarcinoma having lower HRD1 or higher SIRT2 expression levels tend to survive longer." (PMID 31932479, 2020). "We then analyzed the correlation between the overall survival of lung adenocarcinoma patients and HRD1 or SIRT2 expression by using Gene Expression Profiling Interactive Analysis (GEPIA) transcriptome sequencing (RNA-Seq) data sets." (PMID 31932479, 2020). "However, Meta‐analysis from several lung adenocarcinoma studies revealed that the overall SIRT2 level exhibited no apparent difference between cancer and normal tissue." (PMID 36453571, 2023). "Consistent with this, mice lacking Sirt2 develop multiple epithelial malignancies, including pancreatic ductal adenocarcinoma (PDAC) and lung adenocarcinoma (LACA)." (PMID 27637077, 2016).
myocardial infarction (5 papers, 2015 to 2024). Gross necrosis of the myocardium, as a result of interruption of the blood supply to the area, as in coronary thrombosis. "Over-expression of LncHrt protects the heart from myocardial infarction, with SIRT2 acting as an LncHrt interacting protein in cardiometabolic regulation." (PMID 39226168, 2024). "Furthermore, in acute myocardial infarction (AMI), functional DNA sequence variants (DSVs) can alter the SIRT2 levels by affecting the transcriptional activity of the SIRT2 promoter, leading to the progression of AMI into severe disease." (PMID 36101744, 2022). "SIRT2 predicts future atrial fibrillation prevalence in coronary artery disease (CAD) and myocardial infarction." (PMID 36101744, 2022). "Furthermore, in myocardial infarction, maintaining SIRT2 activity can interfere with the interaction between CDK5 and SIRT2 through the interaction between LncHrt and SIRT2, thereby activating the downstream LKB1-AMPK cascade to maintain the balance of cardiac metabolism." (PMID 36101744, 2022).